CD4 (CD4 molecule)
Diseases named in the same sentence as CD4 in open-access papers (continued):
Sharing a sentence is not in itself a finding about the gene and the disease.
viral infection (continued). "Parameters measured were plasma SIV RNA, SIV-antibody response, CD4+ T lymphocyte subsets and in vivo CD8+ cell-suppression of virus infection." (PMID 17132170, 2006). "In contrast, some preterm infants with systemic bacterial or viral infections mounted exceptionally robust CD8+, CD4+, and γδ T cell responses, with oligoclonal expansion, terminal differentiation, and coordinated plasma cytokine shifts that persisted well beyond resolution of infection." (PMID 42013158, 2026). "In fact, studies have shown that during persistent viral infection, CD4+ T cells do not become typical exhausted cells, but instead gradually change their differentiation." (PMID 40777021, 2025). "Inactivated vaccines usually present no complications; live vaccines (i.e., varicella, measles, mumps, rubella, and yellow fever), however, are not recommended in cases of severe immunodeficiency (CD4 cell count < 200/μL)." (PMID 40872885, 2025). "We further analyzed GP66+CD4+ T cells according to their expression of TCF1, a transcription factor intrinsically required for the differentiation of viral-specific Tfh cells, and CX3CR1, a maker of terminally differentiated Th1 cells in viral infections." (PMID 40956613, 2025). "CD44+CD4+ and CD44+CD8+ T cells can secrete IL-2 and IFN-γ, with CD8+T cells potentially promoting activation of CD4+T cells through cytokine secretion, thereby exerting anti-infective effects against viral infections, intracellular bacteria, parasites, etc.." (PMID 40266142, 2025). "In viral infection and vaccination procedures multifunctional CD8+ and CD4+ T cells were considered optimized for effector function and associated with enhanced protection, thus supporting the improved efficacy of the observed polyfunctional anti-tumor T cells." (PMID 40236706, 2025). "The role of Themis in mature CD4+ T cells in the context of chronic viral infection has not been reported before." (PMID 40777021, 2025). "In two patients with XLA, we did not detect any specific antibodies following viral infection; however, S-specific CD4 T-cells were significantly stimulated in these patients (fold of activation 39 and 12, respectively)." (PMID 41280926, 2025). "CD4 T cells, the major target of HHV-6B infection, are known to express MHC-II molecules in response to IFNγ as part of inflammatory responses, including responses to virus infections." (PMID 41376632, 2025). "Furthermore, we also analysed another activation indicator, the co-expression of human leukocyte antigen (HLA)-DR and CD38 in CD4+ T cells and CD8+ T cells, which are considered to be expressed during viral infection." (PMID 41373029, 2025). "In addition, even when viral infection persisted in CD3 + cell-depleted animals, viral titers in fLX remained significantly lower (21-fold lower) than in the fLX of persistently infected CD4 + cell-depleted animals." (PMID 40920821, 2025). "Data from LCMV infection mouse model also revealed a gradual upregulation of TIGIT expression during viral infection and sustained at a high level on LCMV-specific CD4+ and CD8+ T cells during chronic phase of infection in response to continuous TCR stimulation." (PMID 40526725, 2025). "CD4+ and CD8+ T cells induced by DENV and ZIKV contributed to protection against viral infection (10, 74, –, 77), with a particular emphasis on the critical role of CD8+ T-cell responses against heterologous serotype infections or flavivirus infections (10, 76, –, 78)." (PMID 38530012, 2024). "Physiologically, infection diseases are associated with an immunological response with consequent activation and increase of T lymphocytes (both CD4+ and CD8+), B lymphocytes and natural killer cells, although after viral infections lymphocyte counts can be reduced." (PMID 38630321, 2024). "Treatment of EM derived CD4+ T cells with 17β-estradiol (E2) prior to viral infection, reduced infection frequency independent of changes in either CCR5 or α4β7 expression frequency." (PMID 39872519, 2024).
viral infection (continued). "The spread of virus infection between the mock treatment and 10 nM RocA treatment was attenuated, both in the magnitude and rate of virus growth in CEM×174 (left) and primary CD4+ T cells over several passages." (PMID 39339982, 2024). "Likewise, CD4+CD8+ cells reportedly play a role in several autoimmune diseases, virus infections, and cancer." (PMID 38275805, 2024). "Another key function of CD4 T cells during viral infection is differentiation into TFH cells and development of antibody producing B cells in germinal centers, thus contributing to long lasting memory against the viral infection." (PMID 38512979, 2024). "CD4+ and CD8+ T cells play significant roles in the body’s defense against viral infections." (PMID 39764446, 2024). "To avoid this problem, we picked the membrane proteins CD4 and CD25 to prepare mAbs to obtain viable Treg cells, which can be used to understand the modification of function and differentiation of Treg cells after virus infection goats." (PMID 38717623, 2024). "Furthermore, DYY significantly adjusted the CD4/CD8 ratio, which are vital for an effective immune response to viral infections." (PMID 39495380, 2024). "Deletion of Mll1 in CD4 T cells led to significant reductions in Bcl6, LEF-1 and TCF-1 expression and consequently resulted in impaired Tfh differentiation of Ag-specific CD4 T cells during acute viral infections or protein immunizations." (PMID 38825646, 2024). "The presence of CD4+ CTL has been mostly reported in tumors, viral infections, aging, and autoimmune diseases, while the knowledge of CD4+ CTL in CNS diseases is relatively lacking." (PMID 38499993, 2024). "However, CD4+ epitopes were especially important in triggering the production of IFN-γ, which is vital against viral infections." (PMID 38629077, 2024). "Instead of CD8 T cells, CD4 T cells are critical for controlling viral infection in SGs by secreting TNFα and IFNγ, which act on nonhematopoietic cells." (PMID 39134803, 2024). "There was an intermittent upregulation in the CD3+, CD4+, and CD8+ T cell sub-population at different time points in this trial, which is indicative of T lymphocyte inducement, a crucial need for recovering from viral infections." (PMID 39605767, 2024). "The phenotype of circulating CD4+ TFH cells has been reported for several other viral infections or vaccinations, with no clear consensus on an overarching subgroup best equipped for supporting antibody production." (PMID 38197178, 2024). "However, the cellular immune response in particular that involves IFN-γ-producing CD4+ and CD8+ T cells is crucial for fighting viral infections." (PMID 38400157, 2024). "Furthermore, FOXP4 was also expressed in CD4 + and CD8 + T cells and necessary for memory T-cell cytokines recall responses to viral infection." (PMID 38429664, 2024). "This suggests that both CD4+ and WC1+ γδ T-cell subsets are important for this expansion and confirm the role of CD4+ T helper cells in activating and stimulating the proliferation of cytotoxic CD8+ T cells during viral infections." (PMID 38357545, 2024). "During persistent viral infection, type-I IFNs orchestrate a dysregulated immune response that leads to disease progression in LCMV, where blocking type-I IFN signaling enhanced virus specific CD4 T cells and resulted in viral clearance." (PMID 39702382, 2024). "Further characterization of CD4+ cells will be helpful to determine specific frequencies of Th1, Th2, TH17, and Treg cell populations over time in this animal model and their role in the response to viral infection." (PMID 38668247, 2024). "In addition, during viral infection, lung CD103+ DCs travel to the regional lymph node and present antigens on MHC II to stimulate CD4+ T cell proliferation." (PMID 36845082, 2023). "In a viral infection, CD4+ and CD8+ T cells perform non-redundant immunologic tasks that support the innate immune system’s ability to control viral replication and nAbs’ capacity to fight infection." (PMID 36679947, 2023).
viral infection (continued). "During a SARS-CoV viral infection, T cells recognize the viral antigens presented by MHC class I, which induce cytotoxic activity of CD8+ T cells and MHC class II that present peptides to CD4+ T cells." (PMID 36982991, 2023). "CD4+ T-helper cells aid other cells in their cytotoxic activity, activating NK cells and CD8+ T lymphocytes via cytokine release, with both cell types explicitly targeting cells degenerated due to viral infections or malignant processes." (PMID 37444491, 2023). "Although CD4+ and CD8+ T lymphocytes have been shown to play major roles in controlling the viral infection through release of cytokines such as TNF-α or direct cytotoxicity, the complete function of these cells during DENV infections remains to be further investigated." (PMID 37457689, 2023). "Evidence suggests that effector CD4+ T cells have strong protective roles during viral infection that is independent of their helper activities." (PMID 37268634, 2023). "Moreover, HPV vaccines have been associated with increased levels of cytokines (IL-2, IL-6, IL-1α, and IL-1β) and with the induction of IFN-γ-producing CD4+ and CD8+ T-lymphocytes, cytotoxic cells that clear viral infections." (PMID 38068369, 2023). "Thus, Dim1 and Dim2 axes discriminated CD4+ T cells from healthy RMs to SIV-infected RMs, revealing the impact of viral infection on gene expression." (PMID 37656815, 2023). "CD4+ T lymphocytes are closely related to the body’s immunity and a decrease in CD4+ T lymphocytes often indicates an increased likelihood of opportunistic infections such as Pneumocystis carinii pneumonia (PCP) or viral infections." (PMID 37051301, 2023). "The correct ratios of immune subsets are known to be critical during viral infections, such as the CD4/CD8 ratio in HIV-infection, or the total CD4+ and CD8+ T-cells producing IFN-γ or TNF-α as predictors of the immune response after vaccination against tuberculosis and herpes zoster." (PMID 36875099, 2023). "During viral infections (SIV, HIV, Influenza), these cytolytic CD4+ T cells may contribute to the control of viral replication through multiple effector mechanisms including direct cytolysis of infected cells." (PMID 38001069, 2023). "Next, we compared the cytokine-producing ability of T cells with respect to CD4+hi, CD4+lo, CD8+ T cells and compared them with HCs results indicates that there is a significant increase in the cytokine+ CD4+ T cells and CD8+ T cells during chronic viral infection when compared to HCs." (PMID 37163092, 2023). "Most studies utilize HIV-1 reporter viruses pseudotyped with VSV-G or CXCR4-tropic envelopes for bulk CD4+ T cells, which do not precisely model the fate of CCR5+CD4+ T cells upon viral infection." (PMID 36821374, 2023). "When the number of T cells or the ratio of CD4+/CD8+ is reduced, it often indicates immunosuppression, like malignant tumors or viral infections, and when the ratio is increased, autoimmune diseases may occur." (PMID 37958131, 2023). "Finally, similar to the other models of viral infections, the frequency of virus-specific CD8 IFN-γ-producing cells was substantially higher than the IFN-γ producing CD4 T cells during acute infection and after viral clearance." (PMID 37812637, 2023). "CD4+ and CD8+ T cells play a vital role in the defense against viral infection." (PMID 36835584, 2023). "An additional comparative study between infected and non-infected vaccinated CD4+/CD8+ T cell depleted birds will determine if the phenotype is due to combined T cell depletion or induced by a secondary bacterial or viral infection." (PMID 36992357, 2023). "Moreover, they provide protection against future infections with the presence of memory CD4+ and CD8+ T cells that can respond quickly to new virus infections." (PMID 37587490, 2023).
viral infection (continued). "Memory CD4+ T cell subsets are regarded as the predominant cellular compartment of the HIV reservoir, but monocytes and derivative macrophages or dendritic cells also play a role in the persistent virus infection." (PMID 35572626, 2022). "During viral infection, CD4 and CD8 T cells execute non-redundant immunological functions that complement the ability of innate immunity to initially contain viral replication and the efficacy of antibodies to prevent infection." (PMID 36142588, 2022). "EBNA-1-specific CD4 T cells with myelin cross-reaction produce IFN-γ, but they differ from EBNA-1 monospecific CD4 T cells in their ability to produce interleukin-2, indicative of a polyfunctional phenotype, as found in chronic HIV-1 or controlled EBV viral infections." (PMID 35894054, 2022). "In Human Bronchial Epithelial Cells (HBEC) and patient-derived primary CD4+ T cells without viral infection, there was a significant positive correlation between CAI and translational efficiency of mRNAs regardless of viral infection or cultured time." (PMID 36760235, 2022). "Instead, ADCP and complement-mediated functions play a role in suppressing virus infection in CD4 T cells, although virus control was not achieved in other cell types such as monocytes which also harbor the virus." (PMID 34986207, 2022). "Notably, Tfh cells from both virus infection and OVA immunization clustered in a separate node than CD4+CD44+GP66+ T cells, again in line with previous reports relating the TCR α chain to CD4+ cell fate decisions." (PMID 36028771, 2022). "Δ382 SARS-CoV-2 infected patients had higher CD4+ and CD8+ T cells expressing TNF-α than WT infected patients following peptide stimulation, indicating a more robust SARS-CoV-2 specific T cell response in patients with mutant virus infection." (PMID 34716845, 2022). "We review the use of STxB for the cross-presentation of tumor or viral antigens in a MHC class I-restricted manner to induce humoral immunity against these antigens in addition to polyfunctional and persistent CD4+ and CD8+ T lymphocytes capable of protecting against viral infection or tumor growth." (PMID 35324699, 2022). "A relatively small proportion of the entire CD4 cell compartment is infected, and the progressive CD4 lymphopenia characteristic of HIV-infected individuals is probably not the result of direct viral infection." (PMID 36072945, 2022). "In line with this, our data showed that CD4 and CD8 T cell subsets and B cells had poor recovery in the group with cardiac dysfunction, and we know these subsets, particularly T cells, are essential for the control of viral infection." (PMID 35407485, 2022). "The addition of ATLG impacted long-term immune reconstitution on the CD4+ subsets, but this did not translate into higher rate of relapse or viral infection." (PMID 35207379, 2022). "Indeed, older studies have observed that viral infections with RNA viruses, which can trigger TLR3 activation, also induce an IL-12-independent induction of Th1 CD4+ T cell and IgG2a responses." (PMID 35296089, 2022). "CD4+ and CD8+ T cells are important immune components against intracellular viral infection." (PMID 36439228, 2022). "In our model, TRAIL+ NK cells failed to control CD4+ T cell response attacking to target cells, unlike the condition during chronic viral infection." (PMID 36388880, 2022). "Peripheral CD4+CD8+ DP T cells are a phenotypically and functionally heterogeneous population depending on their origin and pathologic context, and their roles in the pathogenesis of autoimmune diseases, viral infections, and cancers are under ongoing debate." (PMID 35062294, 2022). "In addition, CD4+ T cell help is vital for the quantity and quality of nAb and CD8+ T cell responses against virus infection." (PMID 35044832, 2022).
viral infection (continued). "We further find that these bNAbs block the death of abortively infected bystander CD4 T cells when added at the high concentrations needed to block cell-to-cell transmission but not at the lower concentrations blocking cell-free virus infection." (PMID 34418431, 2021). "CD4+ T cell percentage was ~10-fold low compared to CD8+ T cells based on the evaluation of the early activation marker, CD69, together with HLA-DR (marker of cellular activation) after viral infection in both groups of individuals." (PMID 34571855, 2021). "Here, the production and characterization of mAbs against CD8 T lymphocytes were successfully achieved; furthermore, the comparative immune responses between CD4 and CD8 T cells after viral infection and immuno-stimulation were investigated using these newly generated mAbs." (PMID 33467734, 2021). "In our model, metastatic disease promotes compartmentalised CMV reactivation in latently infected individuals, possibly triggered by an unknown winter virus infection; in turn, CMV stimulates expansion of CD4+ TEM cells prior to immunotherapy." (PMID 33664251, 2021). "Both CD4+ and CD8+ T cells are involved in protection against viral disease." (PMID 34211021, 2021). "Such focal hyperactivation of CD8+ T cells but not CD4+ T cells is similar to those of other acute viral infections and vaccines but were relatively short-lived in peripheral blood." (PMID 34867943, 2021). "In addition, Selplg-/- T cell survival was cell-intrinsic as both CD4+ and CD8+ virus-specific T cells exhibited greater persistence as memory cells in WT hosts after viral infection." (PMID 34326837, 2021). "Whereas, the CD3E+CD8A+CD4− clusters contributed substantially to all of top 20 TCR data in three groups’ integrated data, which indicated expanded CD8+ T cell clones contributing to immune response to viral infection." (PMID 34580278, 2021). "Although Th1 and Th17 responses are advantageous in acute viral infections, it is possible that during chronic infections, such as CHC, these CD4+ T cell responses are skewed to Th2 cells and Tregs, CD4+ T cell phenotypes that are less efficient for viral clearance." (PMID 33777278, 2021). "Chronic viral infections such as human immunodeficiency virus or hepatitis C virus infection may consume a large number of TSCM cells, complicating the analysis of CD4+ TSCM results." (PMID 34327142, 2021). "Whilst the suppression of activated CD4+ T cell anti-viral activity at the local site of latent monocytes would enable persistence of the virus infection, it does not entirely explain why activated immune cells are recruited." (PMID 33912186, 2021). "CD4+ T cells migrate to the DRG and secrete IFN-γ at 7 days after viral infection." (PMID 34884605, 2021). "The decrease of lymphocyte subsets was considered to be the main manifestation of viral infection; we speculate that the observed decrease in CD3+ T cells in this study might be related to the decrease of CD4+ T cells and the increase of CD8+ T cells." (PMID 34256745, 2021). "Here, we analyzed CD32+CD4+ T cells in different tissues from two NHP models frequently used in biomedical research: AGM and cynomolgus MAC and investigated their dynamics in response to a viral infection." (PMID 34220857, 2021). "Clarifying the role of follicular CD4 and CD8 T-cells in the context of viral infection can be of great value in confirming a viral-triggered autoimmune response in SjS, but a specific strategy for the characterization of these cells in peripheral blood and target organs is still needed." (PMID 33603079, 2021). "CD4+ and CD8+ T cells play key roles in containing and resolving viral infections." (PMID 35965490, 2021). "On the other hand, in chronic viral infection models, high levels of IFNI have been correlated with reduced numbers of CD4+ T cells, suggesting that sustained IFNI exposure could deplete CD4+ T cells in the TME." (PMID 33801234, 2021).